LINC00922 (long independently transcribed non-coding RNA 922)
Synonyms: Lnc-LALC
Gene: Long non-coding RNA gene on chromosome 16 (65,284,493 to 65,576,352, reverse strand). Ensembl gene ENSG00000261742.
Diseases named in the same sentence as LINC00922 in open-access papers:
LINC00922 is named in the same sentence as 10 diseases in open-access papers, as found by Europe PMC text mining. Sharing a sentence is not in itself a finding about the gene and the disease. The quoted sentences say what the papers report.
gastric cancer (3 papers, 2022 to 2025). A primary or metastatic malignant neoplasm involving the stomach. "Additionally, LINC00922 has been shown to aggravate the malignancies of various types of cancers, including lung cancer, colorectal cancer, ovarian cancer, and gastric cancer." (PMID 40004153, 2025).
breast carcinoma (2 papers, 2022). "First, experiments using ectopic expression of Linc00922 revealed that it increases tumor growth in xenograft mouse models of breast cancer through inhibition of NKD2, thereby enhancing breast cancer metastasis to the lung and the liver." (PMID 36139687, 2022). "LINC00922 is obviously overexpressed in breast cancer tissues and cell lines, and therefore increasing the expression of the miR-424-5p/BDNF axis can reduce the expression of LINC00922 and weaken its effects on promoting the proliferation, apoptosis, migration and invasion of breast cancer cells." (PMID 35409396, 2022).
lung carcinoma (2 papers, 2022 to 2025). "For instance, previous studies suggested that upregulation of LINC00922 promoted lung cancer cell proliferation." (PMID 35428261, 2022).
ovarian carcinoma (2 papers, 2021 to 2025). A malignant neoplasm originating from the surface ovarian epithelium. "The potential binding miRNAs (285 miRNAs) of LINC00922 were predicted by the LncBase Predicted v.2 online database, of which 11 miRNAs were significantly down-regulated in ovarian cancer tissues through analysis of miRNA-OC dataset GSE119055." (PMID 34116704, 2021).
lymph node metastasis (1 paper, 2023). "Besides, the expression of LINC00922 was higher in CRC patients with distant or lymph node metastasis than those without distant or lymph node metastasis." (PMID 37789393, 2023).
preeclampsia (1 paper, 2023). Preeclampsia is a hypertensive disorder of pregnancy that is characterized by new-onset hypertension with proteinuria presenting after 20 weeks of gestation, and depending on mild or severe forms may initially present with severe headache, visual disturbances, and hyperreflexia. "Increased LINC00922 in preeclampsia regulates the proliferation, invasion, and migration of placental trophoblast cells, and arrest of the cell cycle in G0/G1 phase." (PMID 37894897, 2023).
tumor (5 papers, 2021 to 2022). "It is worth noting that the downregulation of LINC00922 decreased the number and diameter of metastatic nodules colonized of the lungs in the tumor metastasis model of nude mice." (PMID 35444700, 2022). "Taken collectively, these findings suggest that FSTL3 and LAMC1 are involved in tumor biology and targeting LINC00922 may be an effective therapy in GC patients." (PMID 35511773, 2022). "Moreover, in vivo experiments have shown that Linc00337, Linc00460, Linc00518, Linc00922, Linc01119, and Linc02163 induce tumor growth and metastasis in vivo which suggests that they could be potential targets for developing novel anti-metastatic therapeutics." (PMID 36139687, 2022). "In addition, HE staining suggested knockdown of LINC00922 inhibited tumor infiltration." (PMID 35428261, 2022). "As similar to the results of the in vitro study, knockdown of LINC00922 repressed the tumorigenicity of HGC-27 cells, and repressed the tumor growth and weight." (PMID 35428261, 2022). "Functionally, LINC00922 knockdown blocked OC cells proliferation, invasion, migration and EMT in vitro and tumor growth in vivo." (PMID 34116704, 2021).
cancer (3 papers, 2022 to 2025). A tumor composed of atypical neoplastic, often pleomorphic cells that invade other tissues. "Aberrant expression of LINC00922 has been revealed to be associated with cancers." (PMID 35428261, 2022). "However, LINC00922 overexpression blocked SIRT3 recruitment to the ETS1 promoter and then increased ETS1 transcription by increasing H3K27cr level in this region, ultimately promoting cancer metastasis." (PMID 37789393, 2023).
LINC00922 also shares sentences with these, for which no sentence is quoted: colorectal cancer (1 paper); osteosarcoma (1).